SMARCA4 (SWI/SNF related BAF chromatin remodeling complex subunit ATPase 4)
Diseases named in the same sentence as SMARCA4 in open-access papers (continued):
Sharing a sentence is not in itself a finding about the gene and the disease.
small intestinal tumor (2 papers, 2024). "Immunohistochemical analysis demonstrated positivity for Cytokeratin 7 (CK7), Transcription Termination Factor 1 (TTF1) and SWI/SNF-related, matrix-associated, actin-dependent regulator of chromatin, subfamily A, member 4 (SMARCA4) in the metastatic small intestinal tumor." (PMID 39659798, 2024). "During treatment, a progressing small intestine tumor was discovered, resected, and identified as SMARCA4-UT metastasis through immunohistochemistry, leading to a revised diagnosis of SMARCA4-UT with brain and small intestine metastases." (PMID 39360100, 2024).
Stroke (2 papers, 2021 to 2024). Sudden impairment of blood flow to a part of the brain due to occlusion or rupture of an artery to the brain. "LEF1, a brain endothelium-specific transcription factor, has been associated with vascular remodeling and post-stroke angiogenesis, and SMARCA4 with cardio–cerebral–peripheral vascular diseases in GWAS." (PMID 35008743, 2021). "Consistent with our findings, other authors reported an enrichment in molecular processes related to cardiomyocyte death, implicating PTEN and inflammation, including AQP9, PTEN, or SMARCA4 (recognized for its involvement in heart fibrosis), in the blood of CE stroke patients." (PMID 38673963, 2024).
Superior Vena Cava Syndrome (2 papers, 2026). A condition that occurs when the obstruction of the thin-walled SUPERIOR VENA CAVA interrupts blood flow from the head, upper extremities, and thorax to the RIGHT ATRIUM. "The clinical presentation of SMARCA4‐UT lacks specific manifestations but commonly includes dyspnea, chest pain, weight loss, fatigue, superior vena cava syndromes, and pleural invasion." (PMID 41577374, 2026).
T-cell lymphomas (2 papers, 2021 to 2025). "Components of the SWI/SNF complex are recurrently altered in many T-cell lymphomas, and SMARCA4 (BRG1) is dephosphorylated upon CDK9 inhibition, contributing to reactivation of gene expression." (PMID 41309546, 2025).
undifferentiated gastric carcinoma (2 papers, 2026). "Cytological examination and immunohistochemical analysis of the EUS-FNA specimen confirmed the diagnosis of SMARCA4-deficient undifferentiated gastric carcinoma." (PMID 42052459, 2026). "This case underscores the importance of clinical awareness and prompt diagnostic evaluation, particularly the value of EUS-FNA, in the early identification of SMARCA4-deficient undifferentiated gastric carcinoma, which may ultimately contribute to improved clinical outcomes." (PMID 42052459, 2026).
ADNP syndrome (1 paper, 2020). "ADNP showed relatively reduced expression in the ADNP syndrome cerebellum, which was also observed for 25 additional genes (representing >50% of the tested genes), including NLGN1, NLGN2, PAX6, SMARCA4, and SNAP25, converging on nervous system development and tauopathy." (PMID 32661233, 2020).
AIDS (1 paper, 2024). A syndrome resulting from the acquired deficiency of cellular immunity caused by the human immunodeficiency virus (HIV). "In this study, we present a rare and intriguing patient with thoracic SMARCA4-deficient undifferentiated tumors (SMARCA4-UT) who also suffered from acquired immune deficiency syndrome (AIDS)." (PMID 39850892, 2024). "Our study presented a rare case of thoracic SMARCA4-deficient undifferentiated tumors and AIDS, suggesting that first-line immunotherapy plus anti-angiogenic drugs as a potential therapeutic option for SMARCA4-UT patients under specific conditions." (PMID 39850892, 2024). "This case highlights the potential of immunotherapy and anti-angiogenic drugs as a viable treatment option for thoracic SMARCA4-deficient undifferentiated tumors, particularly in patients with comorbid conditions such as AIDS." (PMID 39850892, 2024).
bipolar disorder (1 paper, 2018). A disorder of the brain that causes unusual shifts in mood, energy, activity levels and the ability to carry out day-to-day tasks. "The variants are in the Npas2, Cp, Polr3c, Smarca4, Trpv1, and Slc5a7 genes, and many of these genes’ products are in pathways implicated in human bipolar disorders." (PMID 29768498, 2018).
carcinoma of the parotid gland (1 paper, 2015). "Our study apparently adds two tumor types to the spectrum of cancers observed in carriers of SMARCA4 mutations, i.e., the ovarian immature teratoma and carcinoma of the parotid gland." (PMID 25886974, 2015).
developmental disability (1 paper, 2019). Disorders in which there is a delay in development based on that expected for a given age level or stage of development. "Coffin–Siris syndrome (CSS) is a developmental disability, caused by genomic variants in the gene SMARCA4, in addition to other known genes, but the full spectrum of SMARCA4 variants that can cause CSS is unknown with 40% of cases not having molecular confirmation." (PMID 31160358, 2019).
dyslipidemia (1 paper, 2024). "Numerous studies have shown that SMARCA4 may influence the development of AMI by controlling vascular smooth muscle.In the current research, there was no substantial association between the present dyslipidemia in CAD patients and SMARCA4 rs1122608 SNP genotypes." (PMID 38165587, 2024).
endometrioid tumor (1 paper, 2024). A benign, borderline, or malignant epithelial tumor of the female reproductive system characterized by the presence of glands and/or cysts lined by neoplastic cells that resemble endometrial cells. "All five primary cell line samples showed multiple gene alterations previously associated with endometrioid tumors including ARID1A, PTEN, and SMARCA4." (PMID 39240189, 2024).
endometriosis (1 paper, 2022). The growth of functional endometrial tissue in anatomic sites outside the uterine body. "Most notably, ARID1A in endometriosis-related OC, SMARCA4, and SMARCB1 in hypercalcemic type small cell ovarian carcinoma (SCCOHT), ACTL6A, CHRAC1, RSF1 amplification in high-grade serous OC." (PMID 36430148, 2022).
Fibroadenoma (1 paper, 2022). A benign tumor of the breast characterized by the presence of stromal and epithelial elements. "The right-sided breast lump which was diagnosed clinically as a fibroadenoma later turned out to be stage IIb pT3N0M0 metaplastic breast carcinoma with BRCA1 positivity and mutations in SMARCA4." (PMID 36027825, 2022).
ganglioneuroma (1 paper, 2022). A benign neuroblastic tumor of the sympathetic nervous system that occurs in childhood. "Moreover, cases of SMARCA4-UT with ganglioneuroma and enchondroma are very rare." (PMID 35151345, 2022).
goblet cell carcinoma (1 paper, 2023). An aggressive type of endocrine tumor of the appendix presenting equally in males and females in the fifth decade of life and manifesting with a palpable mass and abdominal pain or acute appendicitis. "Most of these mutations were also identified in other studies; for example, mutations in KDM6A, KMT2D, SMARCA4, and ARID1A have been previously reported not only in appendiceal adenocarcinomas but also in appendiceal goblet cell carcinomas." (PMID 37566041, 2023). "Both SMARCA4 and ARID1A are mutated in appendiceal goblet cell carcinoids, mixed goblet cell carcinoid–adenocarcinomas, and some appendiceal mucinous adenocarcinomas and adenocarcinomas." (PMID 37566041, 2023).
hereditary cancer syndromes (1 paper, 2024). "The absence of SMARCA4 from this list reflects the fact that its association with hereditary cancer syndromes has not yet been widely recognized, largely due to the scarcity of reports." (PMID 39439958, 2024).
Hirsutism (1 paper, 2021). Abnormally increased hair growth referring to a male pattern of body hair (androgenic hair). "Almost all patients with genetic alterations in SMARCA4 were reported to have hirsutism, thick eyebrows, long eyelashes, and a less coarse face." (PMID 34706719, 2021).
Hydrocephalus (1 paper, 2023). Hydrocephalus is an active distension of the ventricular system of the brain resulting from inadequate passage of CSF from its point of production within the cerebral ventricles to its point of absorption into the systemic circulation. "In addition, BAF mouse models showing hydrocephalus were established for Smarca4/Brg1 and Arid1b." (PMID 37219662, 2023).
hyperphosphatemia (1 paper, 2019). Abnormally high level of phosphate in the blood. "In adult, the abnormal expression of Smarca4 may increase the risk of VC in CKD patients with hyperphosphatemia." (PMID 30973285, 2019).
Hypertension (1 paper, 2019). The presence of chronic increased pressure in the systemic arterial system. "Our results suggest that rs1464890 and rs4507692 (ZC3HC1), rs11879293 (SMARCA4) and rs1122608 (SMARCA4) were conducive to play a protective role to against the risk of hypertension." (PMID 31507094, 2019). "The genotype “G/A‐A/A” of rs11879293 and the genotype “G/T‐T/T” of rs1122608 in SMARCA4 were significantly associated with decreasing the hypertension risk." (PMID 31507094, 2019). "The genotype “G/A‐A/A” of rs11879293 in SMARCA4 was significantly associated with decreasing the risk of hypertension under the dominant model (OR = 0.70; 95% CI = 0.49–0.99, p = .044)." (PMID 31507094, 2019). "In this study, we aimed to evaluate the association between genetic variants of ZC3HC1 and SMARCA4 and hypertension risk in the Chinese Han population." (PMID 31507094, 2019). "The present study suggested that ZC3HC1 and SMARCA4 polymorphism may conducive to play a protective role against the hypertension risk." (PMID 31507094, 2019). "Rs1122608 in SMARCA4 was also significantly associated with a decreased risk of hypertension in the dominant model (OR = 0.61; 95% CI = 0.38–0.99, p = .047 for the “G/T‐T/T” genotype) and log‐additive model (OR = 0.61; 95% CI = 0.38–0.98, p = .038), respectively." (PMID 31507094, 2019). "The Agena MassAssary platform was used to determine the genotypes of eight SNPs in ZC3HC1 and SMARCA4 from 350 hypertension patients and 483 healthy controls." (PMID 31507094, 2019). "For the current study, we evaluated the association between eight SNPs in SMARCA4 and ZC3HC1 and hypertension risk, and aimed to find the relations of these SNPs and hypertension risk in Han Chinese population." (PMID 31507094, 2019). "In our research, we found rs11879293 and rs1122608 in SMARCA4 seemed to have strong protective effects on the hypertension." (PMID 31507094, 2019). "However, few studies have examined the association between SMARCA4 and ZC3HC1 and hypertension risk." (PMID 31507094, 2019).
invasive carcinoma (1 paper, 2024). A carcinoma that is not confined to the epithelium, and has spread to the surrounding stroma. "Moreover, the tumor cells were negative for SMARCA4/BRG1 in invasive carcinoma but not in HSIL/CIN3." (PMID 38178127, 2024).
Langerhans cell histiocytosis (1 paper, 2024). Langerhans cell histiocytosis (LCH) is a systemic disease associated with the proliferation and accumulation (usually in granulomas) of Langerhans cells in various tissues. "In the trial comprising 20 patients, one individual diagnosed with non-Langerhans cell histiocytosis showed a loss of SMARCA4 expression." (PMID 39439958, 2024).
lung neoplasm (1 paper, 2022). A benign or malignant, primary or metastatic neoplasm involving the lungs. "When encountering a poorly differentiated lung neoplasm, another diagnostic consideration would be “thoracic SMARCA4-deficient undifferentiated tumor”." (PMID 35538551, 2022).
lung neuroendocrine tumors (1 paper, 2025). "The literature indicates that approximately 3%-7% of lung neuroendocrine tumors harbor SMARCA2 and SMARCA4 mutations." (PMID 40661782, 2025).
lung sarcomatoid carcinoma (1 paper, 2023). A rare, aggressive, poorly differentiated, non-small cell lung carcinoma characterized by the presence of a sarcomatoid component often associated with giant cell differentiation. "Our aim was to determine the features of SMARCA4 and SMARCA2 deficiency in lung sarcomatoid carcinomas." (PMID 36178285, 2023). "The aim of our study was to examine SMARCA4 and SMARCA2 profiles in sarcomatoid carcinomas of the lung." (PMID 36178285, 2023).
lung squamous cell carcinoma (1 paper, 2023). "SMARCA4 deficiency is associated with undifferentiated thoracic carcinoma and 3q gain is a characteristic feature of lung squamous cell carcinoma (LUSC) rather than LUAD36." (PMID 37045996, 2023).
mantle cell lymphoma (1 paper, 2023). Mantle cell lymphoma is a rare form of malignant non-Hodgkin lymphoma affecting B lymphocytes in the lymph nodes in a region called the ``mantle zone''. "In mantle cell lymphoma (MCL), recurrent mutations have been observed in SMARCA4 (mutation frequency ~ 6-10%), ARID2, ARID1A, and ARID1B (mutation frequency ~ 3-6% each)." (PMID 36810086, 2023).
metastasis (1 paper, 2024). The spread or migration of cancer cells from one part of the body (where they first appeared) to another. "Finally, one analysis demonstrated significantly worse survival for SMARCA4/KRAS-co-mutated patients as they presented at a higher rate of Stage IV NSCLC with a significantly higher propensity of brain or liver metastasis." (PMID 39063938, 2024).
oral squamous cell carcinomas (1 paper, 2023). "However, the biological function and mechanism of SMARCA4 in oral squamous cell carcinoma (OSCC) remain unclear." (PMID 36902184, 2023).
otosclerosis (1 paper, 2024). Formation of spongy bone in the labyrinth capsule which can progress toward the stapes (stapedial fixation) or anteriorly toward the cochlea leading to conductive, sensorineural, or mixed hearing loss. "While the SERPINF1 gene was found to lack sufficient evidence in relation to the etiology of otosclerosis, a recent publication has suggested that a variant of SMARCA4 might be the cause of otosclerosis." (PMID 38327547, 2024).
ovarian endometrioid carcinoma (1 paper, 2025). "These included alterations in RAD51C, NOTCH4, SMARCA4, SMARCA1 and JAK1 in ovarian endometrioid carcinomas and SMARCA4 genes in ovarian mucinous carcinomas." (PMID 40981433, 2025).
ovarian mucinous carcinomas (1 paper, 2025). "We also detected mutations in the chromatin modifier gene SMARCA4 that had not been previously reported in ovarian mucinous carcinomas." (PMID 40981433, 2025). "In addition to identifying genes previously known to be involved in these tumors, we identified alterations in RAD51C, NOTCH4, SMARCA1/4, and JAK1 in ovarian endometrioid, ESR1 in uterine endometrioid, and SMARCA4 in ovarian mucinous carcinomas." (PMID 40981433, 2025).
Pleural effusion (1 paper, 2025). The presence of an excessive amount of fluid in the pleural cavity. "Furthermore, the administration of nivolumab in the only reported case of SMARCA4-deficient SCLC led to hyperprogressive disease, with worsening pleural effusion and chest wall dissemination of the tumor." (PMID 39888726, 2025).
respiratory failure (1 paper, 2022). The significant impairment of gas exchange within the lungs resulting in hypoxia, hypercarbia, or both, to the extent that organ tissue perfusion is severely compromised. "We presented a case of SMARCA4-UT in a 50-year-old man with progressively worsening respiratory failure." (PMID 36452500, 2022).
Retinal dystrophy (1 paper, 2019). Retinal dystrophy is an abnormality of the retina associated with a hereditary process. "Here, we report an individual harboring a de novo missense SMARCA4 variant falling outside the central domains who presented with mild intellectual disability, mild and not distinctive dysmorphic features, short stature, tooth agenesis, and retinal dystrophy." (PMID 30973214, 2019).
rhabdoid tumor predisposition syndrome types 1 (1 paper, 2023). "SMARCB1 and SMARCA4 germline mutations define rhabdoid tumor predisposition syndrome types 1 (RTPS1) and 2 (RTPS2), respectively." (PMID 37508611, 2023).
Sepsis (1 paper, 2024). Sepsis is defined as life-threatening organ dysfunction caused by a dysregulated host response to infection. "Under nonresolving inflammatory signals, such as in sepsis, the overexpression of Mir222 contributes to morbidity by targeting Smarca4, a chromatin remodeling component that participates in the SWI/SNF complex." (PMID 39235454, 2024).
signet ring cell carcinoma (1 paper, 2024). A usually aggressive, poorly differentiated invasive adenocarcinoma characterized by the presence of malignant glandular cells in which the nucleus is pressed to one side by the presence of intracytoplasmic mucus. "Notably, the frequency of the signet ring cell carcinoma, which is an unique subtype of adenocarcinoma, was significantly lower in the SMARCA4-mutated group than in the SMARCA4-normal group, with 3 cases (15.8%) versus 100 cases (42.2%); this difference was statistically significant (p = 0.044)." (PMID 38610978, 2024).
small cell carcinoma of the cervix (1 paper, 2024). "Although we did not identify SMARCA4 mutations in two of the eight SCLC-Y lines, one of these lines was pathologically not consistent with SCLC and the other was derived from a 26-year-old patient diagnosed with a primary small cell carcinoma of the cervix rather than SCLC." (PMID 38180245, 2024).
soft tissue sarcoma (1 paper, 2025). A malignant neoplasm arising from muscle tissue, adipose tissue, blood vessels, fibrous tissue, or other supportive tissues excluding the bones. "Generally, the first-line treatments for NSCLC patients with SMARCA4 are similar to those for soft tissue sarcoma (STS)." (PMID 41142791, 2025). "Studies suggest that the first-line chemotherapy regimen for NSCLC with SMARCA4-UT is analogous to that employed for soft tissue sarcoma (STS)." (PMID 41142791, 2025).
Tumor of the Esophagus (1 paper, 2024). "This specimen was also reported as a SMARCA4-deficient undifferentiated esophageal tumor." (PMID 38497146, 2024).
tumor predisposition syndromes (1 paper, 2022). "Although our data is clearly limited in this aspect, our findings suggest that NEC-like SMARCA4/ARID1A tumors may also occur in the context of tumor predisposition syndromes." (PMID 36443295, 2022).
undifferentiated carcinoma of gallbladder (1 paper, 2023). "However, to the best of our knowledge, SMARCA4 (BRG1)-deficient undifferentiated carcinoma of gallbladder has not yet been reported." (PMID 37456262, 2023).
uterine cancer (1 paper, 2023). Primary or metastatic malignant neoplasm involving the uterine corpus and/or the cervix. "Same information for predictive models of (b) IDH1-d, (c) SMARCA4-d, (d) CDKN2A-d, (e) HERC2-d, and (f) PTEN-d in central nervous system (CNS) cancers and (g) uterine cancers." (PMID 36883553, 2023).
uterine carcinosarcoma (1 paper, 2021). A usually aggressive malignant neoplasm arising from the uterine corpus and less often the cervix. "DFS analysis shows high SMARCA4 expression is correlated with poor prognosis for the TCGA cases of ACC (p = 0.0023), BRCA (p = 0.034), and uterine carcinosarcoma (UCS, p = 0.017)." (PMID 34675941, 2021).